TNF (tumor necrosis factor)
Diseases named in the same sentence as TNF in open-access papers (continued):
Sharing a sentence is not in itself a finding about the gene and the disease.
gastric cancer (continued). "H. pylori is classified as the definitive carcinogen for gastric cancer in humans, and a gene product of H. pylori possessing TNF-α-inducing activity is thought to act as a tumor promoter for human gastric cancer." (PMID 30341686, 2018). "In addition to these effects on cancer cells, it seems important that the phenotypic changes of mesothelial cells induced by TNF-α, especially the enhancement of MMP-9 secretion, may cause peritoneal metastasis, and thus a poor prognosis for patients with gastric cancer." (PMID 30544870, 2018). "Knock-down of IKKβ or p65 expression in gastric cancer cells reversed H. pylori-induced down-regulation of FAF1 expression and partially blocked H. pylori-induced secretion of inflammatory cytokines TNF-α and IL-8." (PMID 28030825, 2017). "Up-regulation of TNF-α has the capacity to increase the chemokine receptor CXCR4 levels, which promotes the invasiveness of gastric cancer cells." (PMID 27356745, 2016). "This means that inflammation (TNF-α and IFN-γ) can maintain IL-8 secretion by gastric cancer cells and that this can become inhibited by CAM by inhibiting NF-κB activation and AP-1 binding in the IL-8 gene promoter region in gastric cancer cells." (PMID 25729426, 2015). "Tumor necrosis factor-α (TNF-α) plays a crucial role in the development and progression of gastric cancer." (PMID 23326309, 2013). "In other words, OLFM4 knock down enhanced H2O2 or TNF α-induced apoptosis in gastric cancer cells, indicating deletion of OLFM4 made SGC-7901 and MKN45 cells more sensitive to treatment of H2O2 or TNF α." (PMID 22471589, 2012). "Others findings have revealed TNF-α antagonists can inhibit the upregulation of CXCR4 expression by H. pylori, and both it and CXCR4 antagonists can suppress the increased migration of gastric cancer cells in vitro." (PMID 20699000, 2010). "MMP-9 mRNA and protein expression was dose-dependently increased by TNF-α in SNU216 and SNU668 gastric cancer cells." (PMID 19924065, 2009). "Tumor necrosis factor alpha (TNF-α) is an inflammatory cytokine implicated in tumor progression, yet its relationship with established gastric cancer tumor markers has not been fully clarified." (PMID 40299527, 2025). "Taken together, these results reinforce the notion that TNF-α is preferentially tied to tumor-specific factors, whereas its variation in individuals without gastric cancer remains minimal and clinically negligible." (PMID 40299527, 2025). "TNF/TNFR were identified as primary bioactive targets that may mediate the inhibitory effects of AK and GK on gastric cancer." (PMID 39860044, 2025). "Moreover, FLOT1 mediates the levels of heterotypic signaling molecules, including TNF-α, EGF, HGF, and IGF1, across various cancers, such as breast, prostate, and gastric cancer, and oral squamous cell carcinoma." (PMID 40335491, 2025). "Based on public omics data, it was also found that some of these biomarkers showed significant changes in the progression from gastritis to dysplasia and gastric cancer, and were reported to participant in the progression of gastric cancer, such as LEP, CCL2, CD14 and TNF." (PMID 39367502, 2024). "TNFα is defined as the upstream partner of HDGF in gastric cancer cells in 2-D culture; however, in (3D) organoids in culture, HDGF and TNFα are involved in independent signals in the development of H. pylori-infected gastric cancer." (PMID 37047540, 2023). "Similarly, these pathways were overexpressed in gastric cancer - PI3K-AKT (FC 1.23, 95% CI: 1.01-1.44), inflammatory cytokines (FC: 1.49, 95% CI: 1.33-1.65), TNF signaling (FC 1.36, 95% CI: 1.14-1.57)." (PMID 37954072, 2023). "Besides, IL-6 and TNF-α secreted from macrophages induce PD-L1 expression through NF-κB and STAT3 signaling pathways in gastric cancer cells." (PMID 36978108, 2023). "A recent study demonstrated that H2O2, but not TNF-α markedly suppressed the expression of miR-328 in gastric cancer cells." (PMID 37685838, 2023).
gastric cancer (continued). "Experimental studies confirmed that the proliferation inhibition of oridonin on SGC‐7901 cell was related to TNF‐α/AR/TGF‐β signalling pathway axis, which confirmed the prediction of network pharmacology, and elucidated the mechanism of oridonin on gastric cancer." (PMID 37431884, 2023). "Furthermore, the levels of IL-6, IL-10, TNF-α, and VEGF in the gastric cancer cell line were higher than those in normal human gastric mucosal epithelial cells." (PMID 36618075, 2022). "TNF, IL1B, and MMP9 play important roles in the occurrence and development of gastric cancer." (PMID 36200190, 2022). "Remarkably in gastric cancer, artemisinins reverse the IκBα level, prevent NF-κB pathway in a dose-dependent manner, and decrease the generation of downstream inflammatory factors such as TNF-α (tumor necrosis factor-α) and IL-8 (interleukin-8)." (PMID 35197994, 2022). "The pro-inflammatory cytokines IL-1β, TNF, and IL-6 can induce the transition of EMT in head and neck cancers and anti-inflammatory cytokine IL-10 can lead to tumor cell proliferation through an induction of STAT3 activation in gastric cancer cells." (PMID 35283421, 2022). "TNF alpha and CEA may be potential predictors of gastric cancer in patients with benign gastric lesions." (PMID 35186129, 2022). "TNF-α increased integrin αV expression in AGS, NCI-N87, and NUGC3 human gastric cancer cells." (PMID 36613819, 2022). "TNF-α can increase the release of pro-inflammatory cytokines, augmenting apoptosis induced by H. pylori, while monoclonal antibodies targeting TNF-α have been investigated for their potential to prevent inflammation-based gastric cancer." (PMID 36299773, 2022). "Thus, patients with stage I, II, III, and IV stomach cancer have significantly higher overexpression of PYGB (p = 0.043), TNF (p = 0.02), HLA-A (0.05), and EFNB2 (0.001) genes, respectively." (PMID 33828156, 2021). "We demonstrated that FXR signaling antagonist z-guggulsterone reduced gastric cancer cell viability through inhibiting cell proliferation, decreasing intrinsic mitochondrial apoptosis, and downregulating VEGF and TGF-β1 levels but upregulating the TNF-α level." (PMID 33488300, 2021). "The presence of IL-1β-511T, IL-1RN*2/*2, TNF-α-308A, and IL-10 (haplotype ATA/ATA) was connected to a higher risk of noncardia gastric cancer with H. pylori infection." (PMID 30123433, 2018). "Quantification of circulating IL-4, TNF-α, IL-10 and INF-γ level in 17 patients diagnosed with gastric carcinoma and 30 subjects as control population was achieved by ELISA assay (Affymetrix Ebioscience, USA) using a calibration curve with known concentration standard (as described)." (PMID 30526523, 2018). "The analysis revealed an increase in TNF-α gene expression in patients with gastritis; on the other hand, no statistical differences were observed in patients with gastric cancer." (PMID 26719751, 2015). "We observed that Bregs from gastric cancer do inhibit the production of IFN-γ and TNF-α." (PMID 26378021, 2015). "Moreover, gastric cancer cells secreted PGE2 and TNFα that stimulated IL-6 secretion by the stromal cells." (PMID 25785838, 2015). "Thus, some of the gastric cancer cells secreted PGE2 and TNFα stimulating the stromal cells to secrete IL-6 that supported the growth of cancer cells." (PMID 25785838, 2015). "Gastric cancer cells secreted at least PGE2 and TNFα to stimulate IL-6 production by stromal cells." (PMID 25785838, 2015). "Therefore, by induction of TNF from activated macrophages, JHP0290 can potentially contribute to gastric cancer development." (PMID 24223737, 2013). "Levels of CXCR4 and TNF-α mRNA were significantly higher in H. pylori-positive gastric cancers (n = 19) compared to H. pylori-negative ones (n = 15)." (PMID 20699000, 2010).
gastric cancer (continued). "In the same cohort of tumors, TNF-α mRNA expression was also detected by real-time reverse-transcription PCR, and it was found stronger in H. pylori-positive gastric cancers compared to H. pylori-negative ones (4.3 fold, P < 0.01)." (PMID 20699000, 2010). "Among non-smokers, the model included only TNF-α-857 and had a maximum CVC of 9/10 and a higher prediction for gastric cancer risk of (OR = 1.7, 95% CI 1.0–2.7) though showing minimum TA of 0.603 (p = 0.0636)." (PMID 19615068, 2009). "In another study, we have observed a significant increase in serum tumor necrosis factor -α levels among patients with gastric cancer (data not shown)." (PMID 15930805, 2005). "In vivo experiments further revealed that KHSRP silencing markedly increased the infiltration of CD4+, CD8+, Granzyme B+, IFN-γ+, and TNF-α+ cells within the tumor, suggesting that KHSRP could serve as a potential prognostic marker and therapeutic target for gastric cancer." (PMID 39866240, 2025). "BCLAF1 is a key regulator of TNF-α-induced apoptosis, and the phosphorylation of BCLAF1 at Ser290 is involved in the regulation of the DNA damage response, eliminating the phosphorylation of BCLAF1 at Ser290 and suppressing gastric cancer (GC) cell proliferation." (PMID 40732187, 2025). "However, this was not consistent with our data using the recombinant HDGF and TNFα in human gastric cancer 3-D-organoid system." (PMID 37047540, 2023). "We observed that 5-FU-resistant gastric cancer cells were more effective than 5-FU-sensitive gastric cancer cells in skewing macrophages to M2 polarization, characterized by up-regulated expression of CD163, CD206, IL-10, Arg-1 and VEGF-A and down-regulated expression of CD86, TNF-α and IL-12." (PMID 36151545, 2022). "Nevertheless, there was no proof to recognize the link of the PTX3 with TNF-α in gastric cancer." (PMID 32194791, 2020). "A randomized controlled trial in gastric cancer patients who had gastrectomies indicates that DEX, given intraoperatively, has potent immunomodulatory properties that are observed as improvement in the Th1/Th2 ratio and reduction in IL-6 and tumor necrosis factor (TNF)." (PMID 30537999, 2018). "IL-6 secretion from fibroblasts stimulated with conditioned media from three different gastric cancer cell lines was significantly suppressed by IL-1RA but not by anti-TNFα, suggesting the involvement of IL-1 in the mechanisms of IL-6 secretion from fibroblasts stimulated by cancer cells." (PMID 23593346, 2013). "However, TNF-α expression did not significantly differ between gastric cancer patients and healthy individuals after H. pylori exposure." (PMID 22526791, 2012). "Similar to our results, a gastric cancer study found that neither G-CSF, GM-CSF, TGF-β, M-CSF, IL-1β, IL17A, IL-6, TNFα, IL10, IFNγ and IL22 were able to induce MC degranulation, while only adrenomedullin did." (PMID 32722549, 2020). "A recent study by Dr. Baba's laboratory demonstrated that miR-328 expression was markedly suppressed in gastric cancer cells treated with H2O2, but not TNF-α." (PMID 26452256, 2015). "In addition, although the mechanism of action of TNF-α in tumors has been widely proven during recent years, studies have not mentioned the interaction between TNF-α and PTX3 in gastric cancer metastasis and EMT." (PMID 32194791, 2020). "While λ-COS has shown potential in enhancing the immune system and inducing apoptosis of gastric carcinoma cells through Par-4 signaling, it should be noted that λ-COS also increased the secretion of TNF-α, a proinflammatory cytokine, which may have negative effects that require further evaluation." (PMID 37432179, 2023).
periodontal disease (359 papers, 2007 to 2026). "In periodontal diseases, models overexpressing IL-6 or TNF-α mimic inflammatory bone loss, while MMP-9 knockout mice display reduced periodontal degradation." (PMID 41559024, 2026). "Genetic factors, such as variations in cytokine genes (e.g., IL-1, TNF-α), can predispose individuals to heightened inflammatory responses, increasing susceptibility to periodontal disease." (PMID 39852378, 2025). "Previous studies have shown that periodontal disease is caused by bacteria present in dental plaque, which induce the production of inflammatory cytokines, such as TNF-α, IL-1β, and IL-6, thereby forming a cytokine cascade." (PMID 41303285, 2025). "Given the inflammatory nature of periodontal diseases, gingivitis is also linked to increased levels of salivary inflammatory cytokines, including IL-6, TNF-α, IL-1β, IL-8, and IL-10." (PMID 40243684, 2025). "First, the cross-sectional design of the study limits causal inferences regarding the relationship between TMAO, TNF-α, and periodontal disease progression." (PMID 40131489, 2025). "In a periodontal disease mouse model, GC administration led to greater bone loss, fewer osteoblasts, and increased osteoclasts and TNF-α levels." (PMID 41303285, 2025). "Another clinical study in adults confirmed significant associations between the severity of periodontal disease and salivary concentrations of IL-1β and TNF-α." (PMID 41301927, 2025). "The cytokine profile observed—characterized by significant increases in IL-1β, IL-6, TNF-α, and IL-8—indicates that candidiasis in children is associated with an inflammatory state similar to that observed in early-onset periodontal disease." (PMID 41301927, 2025). "For instance, vitamin D has been shown to reduce the expression of cytokines linked to periodontal disease and dementia, such as interleukin-6, interleukin-8, and tumor necrosis factor-α." (PMID 40907543, 2025). "Periodontal disease is associated with elevated inflammatory biomarkers, including IL-1, IL-6, TNF-α, and CRP, which are also elevated in AD." (PMID 40559320, 2025). "The chronic inflammation associated with periodontal disease results in the release of pro-inflammatory cytokines such as interleukin-1 (IL-1), interleukin-6 (IL-6), and tumor necrosis factor-alpha (TNF-α)." (PMID 40283848, 2025). "Disorders of oral microflora such as periodontal disease are associated with various systemic diseases via periodontal disease-causing bacteria and inflammatory cytokines such as TNFα." (PMID 40142822, 2025). "Mogibacterium is a Gram-positive anaerobic rod bacterium, previously isolated from the root canals of patients with periodontal disease, and associated with the induction of IL-8 and TNF in chronic bacterial osteomyelitis and osteonecrosis of the jaw." (PMID 40002950, 2025). "Gingivitis is an inflammation of the gums that is the initial cause of the development of periodontal disease by the activity of Nuclear Factor-kappa B (NF-κB), Interleukin-1β (IL-1β), Interleukin-6 (IL-6), p38, and Tumor Necrosis Factor-α (TNF-α)." (PMID 38978754, 2024). "In case of RA and periodontal disease TNF-α polymorphisms can play a significant role in both, in certain populations." (PMID 38256582, 2024). "Research indicates a notable increase in plasma TNF-α levels among individuals with periodontal disease, which aligns with the loss of gingival attachment and deepening of periodontal pockets." (PMID 38920850, 2024). "While, on the other hand, a close association between elevated TNF-α levels in GCF with periodontal disease has also been demonstrated, supporting its use as a potential biomarker for its diagnosis." (PMID 38431633, 2024). "Obese individuals have higher levels of IL-6 and TNF-α, which make them more susceptible to developing destructive periodontal disease." (PMID 37629193, 2023).
periodontal disease (continued). "Gomeset al.25 noted that salivary IL-1β and TNF-α levels increase in periodontal disease and are associated with the onset and increased severity of the disease, and that their levels decrease after treatment." (PMID 37224312, 2023). "PCOS was linked to increased levels of CRP, interleukin-6, and TNF- α, all of which contribute to chronic low-grade inflammation and raise the risk of periodontal disease." (PMID 38021744, 2023). "Tumor necrosis factor alpha is one of the first proinflammatory cytokines secreted in periodontal disease and causes the onset of periodontal disease by stimulating osteoclast formation and alveolar bone destruction." (PMID 37909201, 2023). "As for C5, it was reported that C5a can induce the activation of C5Ar in a murine periodontal disease and cause significant bone loss with the help of cytokines like IL-17, IL-1β, IL-6, and TNF." (PMID 35571048, 2022). "Periodontal diseases increase levels of circulating IL-1β, IL-6, IL-8, IL-17 and TNF-α, interleukins associated with systemic inflammation and preterm birth." (PMID 35369278, 2022). "Sex steroids, innate and acquired immunity, and higher levels of inflammatory cytokines, including interleukin-1β and tumor necrosis factor-α in men, makes them more susceptible to destructive periodontal disease." (PMID 36012906, 2022). "A significant association between IL-1α and TNF-α and the prevalence of periodontal disease was confirmed." (PMID 34199256, 2021). "The adaptive immune responses in particular, CD4+ T cells and the proinflammatory cytokines IFN-γ and TNF-α are important effectors of bone loss in periodontal disease." (PMID 33672708, 2021). "Concentrations of four pro-inflammatory cytokines (IL-1β, IL-6, IL-8 and TNF-α) linked with periodontal disease were measured in the collected saliva of nine subjects in the probiotic gum group at each timepoint." (PMID 33962608, 2021). "Individuals with cerebral palsy present higher risk to develop periodontal disease due to the reduced salivary flow rate, increased salivary osmolality rate and elevated levels of TNFα, IL-10, IL-6 compared to individuals with individuals with Down syndrome." (PMID 32509226, 2020). "IL-1β and TNF-α are potent pro-inflammatory mediators secreted in response to bacteria and are associated with the pathogenesis and progression of periodontal disease." (PMID 32106858, 2020). "Individuals with CP have higher risk to develop periodontal disease due to reduced salivary flow rate, increased salivary osmolality rate and elevated TNFα, IL-10, IL-6 compared to DS." (PMID 32509226, 2020). "Although the expression of proinflammatory cytokines associated with periodontal disease pathogenesis (such as, IL-1β, IL-6, IL-17A, and TNF) was inhibited, statistical significance was reached only for IL-17A, which was downregulated by 4.9-fold." (PMID 31581596, 2019). "RA patients had a higher bacterial load, a more diverse microbiota, an increase in bacterial species associated with periodontal disease, more clinical attachment loss, and increased production of inflammatory mediators including IL-17, IL-2, TNF, and IFN-γ." (PMID 31182740, 2019). "Numerous studies have shown that susceptibility to periodontal diseases are affected by the polymorphisms of many genes, including interleukin-1 (IL-1), tumor necrosis factor-α (TNF-α), transforming growth factor-beta (TGFβ) and 5-HTT." (PMID 31428137, 2019). "Patients with DM showed a significant higher monocytic TNF-α secretion in the presence of a periodontal pathogen (Porphyromonas gingivalis), which is associated with an increased periodontal disease severity." (PMID 30962800, 2019). "Conversely, the progress of debilitating periodontal diseases is associated with TNF-α, which acts as a primary and early periodontal pathogen-induced inflammatory cytokine in this context." (PMID 30186882, 2018).